CD36 (CD36 molecule (CD36 blood group))
Diseases named in the same sentence as CD36 in open-access papers (continued):
Sharing a sentence is not in itself a finding about the gene and the disease.
gastric cancer (continued). "Notably, CD36-mediated fatty acid metabolism plays a significant role in the growth and metastasis of multiple tumors, including oral cancer, breast cancer, cervical cancer, and gastric cancer." (PMID 33771982, 2021). "Similar findings were reported in gastric cancer, where HFD or CD36 overexpression was shown to enhance the peritoneal dissemination of gastric cancer cells via the AKT-mediated inactivation of GSK3β and the subsequent stabilization of β-catenin." (PMID 37371076, 2023). "CD36, FABPs, and CPT1, which are fatty acid absorption-related molecules, also contribute to the proliferation of gastric cancer cells." (PMID 35625633, 2022). "APOC2 cooperates with CD36 to regulate EMT process via PI3K/AKT/mTOR signaling, which eventually promotes tumor progression and peritoneal metastasis in gastric cancer." (PMID 34459127, 2021). "In gastric cancer, phosphatidylinositol transfer protein cytoplasmic 1 (PITPNC1) upregulates the RNA level of PPARG, and PPARγ then enhances the expression of CD36 and mitochondria CPT1 and thereby elevates FA absorption and promotes FAO and metastasis." (PMID 31410189, 2019). "Among these, the selection of 19 HERSRDEGs such as ANGPT2, ERG1, CD36, NOX4 and TLR2, provides critical insights into the potential roles these genes may play in gastric cancer pathophysiology." (PMID 40061897, 2025). "Similarly, gene expression analysis performed on the TCGA-STAD cohort showed overexpression of CD36 in SARIFA-positive cases, indicating fatty acid metabolism changes in SARIFA areas, which is consistent with previous findings in gastric cancer." (PMID 41228384, 2025). "Finally, further in vivo and in vitro experiments are needed to verify the functional roles of the three genes (CD36, SERPINE1, and GRP) in gastric cancer that were used to construct the RCDRI index." (PMID 41000398, 2025). "The newly constructed RCDRI consisted of four Regulated cell death-related genes (CD36, SERPINE1, TRIML2, and GRP) and has been shown to be an effective predictive marker for the survival of gastric cancer patients and was trained with multiple external datasets." (PMID 41000398, 2025). "Studies have shown that a high‐fat diet upregulates CD36 expression and increases the uptake of FAs by inducing structural changes in CD36 (O‐acylation of S468 and T470 and reduction formation of the C333C272 disulfide bond in CD36), leading to advanced metastasis of gastric cancer." (PMID 39584783, 2024). "Finally, we carried out qRT-PCR analysis of the expression levels of RGS2, GNAI2, ANXA5, MARCKS, CD36, NRP1, and PDE4A in gastric cancer cells." (PMID 38274323, 2024). "Interestingly, the high expression level of both CD36 and OGT predicted a worse clinical outcome in gastric cancer patients." (PMID 37371076, 2023). "In gastric cancer cells, phosphatidylinositol transfer upregulates PPARG and CD36." (PMID 36114448, 2022). "Indeed, palmitate-induced metastasis of gastric cancer is dependent on CD36, and high CD36 expression levels in gastric cancer patients correlate with poor clinical outcome; therefore, there is a possibility that blocking of the CD36–palmitate axis may serve as a potential gastric cancer treatment." (PMID 31847240, 2019). "CD36 contributes to ovarian cancer metastasis, promotes epithelial-mesenchymal transition (EMT) in cervical cancer via TGFβ signaling, and accelerates gastric cancer metastasis through reprogramming lipid metabolism, highlighting its broad involvement in cancer progression." (PMID 36361816, 2022). "To investigate the expression of CD36 in human gastric carcinomas, we searched The Cancer Genome Atlas (TCGA) database and noted that the CD36 gene copy number was significantly elevated in numerous types of GCs compared with that observed in normal gastric tissues." (PMID 31410220, 2019).
hepatocellular carcinoma (60 papers, 2012 to 2025). A malignant tumor that arises from hepatocytes. "Newer studies have also found that caner-associated fibroblasts can promote hepatocellular carcinoma recurrence and metastasis through CD36-mediated fatty-acid metabolism reprogramming." (PMID 39165945, 2024). "CD36-associated fatty acid uptake is also able to promote EMT in hepatocellular carcinoma cell lines, whereas in cervical cancer, the pro-metastatic effect of CD36 was synergistic with TGFβ-induced EMT in cell lines." (PMID 36980201, 2023). "It has been previously shown that increased fatty acid uptake via CD36 is associated with EMT progression in hepatocellular carcinoma cells." (PMID 35008415, 2022). "Other carcinomas such as ovarian carcinoma or hepatocellular carcinoma have also shown an association between CD36 expression and metastasis formation." (PMID 34439279, 2021). "In contrast, studies on hepatocellular cancer (HCC) cells indicated that EMT was closely associated with CD36 expression via Wnt and TGF-β signaling pathways." (PMID 33232276, 2020). "For instance, CD36+ CAFs in hepatocellular carcinoma can uptake oxidized low-density lipoprotein and activate the p38-CEBP-MIF axis to recruit MDSCs, promoting an immunosuppressive environment." (PMID 40826474, 2025). "These functions of CD36 have been reported for cancer cells from different tumor types, including hepatocellular carcinoma (HCC), breast cancer, bladder cancer, stomach cancer, ovarian cancer, head and neck squamous cell carcinoma, lung cancer, and others." (PMID 39967671, 2025). "In summary, FAT/CD36 is strongly associated with the prognosis of NAFLD and hepatocellular carcinoma." (PMID 41458968, 2025). "For instance, fatty acid translocase CD36 expression causes an increase in intracellular fatty acid concentrations and facilitates the process of EMT in hepatocellular carcinoma cells." (PMID 38390305, 2024). "CAFs within hepatocellular carcinoma can also recruit M-MDSCs to hepatocellular carcinoma tissues by promoting macrophage migration inhibitory factor (MIF) secretion in a CD36-dependent manner." (PMID 38609997, 2024). "Gui-Qi Zhu reported that CD36+ CAFs in hepatocellular carcinoma exhibit high lipid metabolism and secrete macrophage migration inhibitory factor via the lipid peroxidation/p38/CEBPs axis, leading to an immunosuppressive TME and tumour stemness." (PMID 38316848, 2024). "Our analysis of TMAs from 13 different cancer indications revealed that all were comprised of over 60% of patients with high CD36, with the exception of Hepatocellular carcinoma (HCC), which was comprised of 57% of patients with high CD36 expression." (PMID 39627379, 2024). "In previous studies, SelK was found to regulate ER stress in hepatocellular carcinoma cells, foam cell formation, and atherogenesis by regulating CD36 palmitoylation on the surface of macrophages." (PMID 39155374, 2024). "At present, there were no approved drugs to treat symptoms of liver fibrosis, and studies showed that HSCs-derived cartilage oligomeric matrix proteins were directly involved in the development of hepatocellular carcinoma in coordination with CD36." (PMID 35035671, 2022). "Their results reveal that CD36 accelerates proliferation and metastasis of hepatocellular carcinoma by enhancing FA absorption through AKR1C2 and jointly affect the FA metabolism." (PMID 36428985, 2022). "Particularly, hepatocellular carcinoma progression was correlated with CD36/fatty acid translocase and high free fatty acid levels via induction of EMT, which was promoted by TGF-β and Wnt signaling." (PMID 34150624, 2021). "Increased CD36 expression in hepatocellular carcinomas reportedly induces EMT and elevates FFA levels." (PMID 34561446, 2021). "CD36 can be a prognostic marker for different cancers, most often of epithelial origins, such as breast cancer, ovary cancer, prostate cancer, or hepatocellular carcinoma." (PMID 32781778, 2020).
hepatocellular carcinoma (continued). "In a previous study we used such a method to delineate the role of FAT/CD36 in adipocytes as well as the signaling pathways involved in the regulation of hepatocellular carcinoma cell proliferation by glucose." (PMID 30905315, 2019). "We previously demonstrated that H2 inhibits fatty acid uptake and lipid accumulation through the downregulation of CD36 in human hepatoma HepG2 cells." (PMID 30429524, 2018). "Fatty acid-enhanced epithelial–mesenchymal transition in hepatocellular carcinoma is mediated by CD36 function." (PMID 30573731, 2018). "CD36 overexpression in human hepatoma cells increases the uptake of fatty acids, whereas a CD36 deficiency significantly impairs fatty acid uptake by peripheral organs such as heart, skeletal muscle, and adipose tissue in rodents." (PMID 22762794, 2012). "In human hepatoma cells, CD36 overexpression significantly increased fatty acid uptake." (PMID 39774047, 2025). "Similarly, in hepatocellular carcinoma models, the CD36 inhibitor SSO combined with anti-PD-1 enhances T cell responses and tumor control." (PMID 41550652, 2025). "Furthermore, the regulatory function of CD36 in EMT has been demonstrated in hepatocellular carcinoma and cervical cancer cells." (PMID 41465497, 2025). "For instance, CD36 overexpression in oral cancer cells significantly stimulates lymph node metastasis and CD36+ cancer‐associated fibroblasts create an immunosuppressive microenvironment in hepatocellular carcinoma to promote tumor progression, suggesting oncogenic roles for CD36." (PMID 41267927, 2025). "There is evidence suggesting that, in some forms of cancer, such as hepatocellular carcinoma, fatty acid uptake through CD36 may promote cancer cell metastasis and distant proliferation." (PMID 32781778, 2020). "CD36 has been repeatedly proposed as a prognostic marker in various cancers, mostly of epithelial origin (breast, prostate, ovary, and colon) and also for hepatic carcinoma and gliomas." (PMID 30069479, 2018). "CD36+ CAFs in hepatocellular carcinoma (HCC) exhibit upregulated lipid metabolism-driven immunosuppression by impairing cytotoxic T lymphocyte activity and elevating PD-1 expression, as demonstrated in murine models." (PMID 40755769, 2025). "Furthermore, CD36+ cancer-associated fibroblasts (CAFs) employ MIF and CD74 to attract CD33+ myeloid-derived suppressor cells (MDSCs), creating an immunosuppressive environment that facilitates immune evasion in hepatocellular carcinoma." (PMID 40051627, 2025). "The combination of ICIs and CD36 inhibitor in a hepatocellular carcinoma (HCC) in vivo model significantly improved the growth inhibitory effect and survival rate compared to ICIs alone." (PMID 39273384, 2024). "Lastly, cirrhotic patients and hepatocellular carcinoma (HCC) patients exhibited increased CD36 expression and reduced PPAR-α expression." (PMID 38248815, 2023). "Moreover, CD36-positive cells were essential for metastasis formation in human oral cancer cells and the TGFβ signaling pathway was activated upon free fatty acid addition in hepatocellular carcinoma cells, resulting in EMT induction." (PMID 31822964, 2020). "OF was also found to be capable of reducing lipid accumulation and cancer formation in non‐B non‐C Hepatocellular carcinoma (HCC) model in CD36 transgenic zebrafish." (PMID 33377648, 2020). "In hepatocellular carcinoma (HCC) cells, CD36 also promotes free fatty acid uptake and epithelial-mesenchymal transition (EMT), accelerating tumor progression and metastasis." (PMID 40028341, 2025). "In hepatocellular carcinoma cells, sulfo-N-succinimidyl oleate (SSO) reduces the EMT phenotype and decreases the migration rate of PA-treated cells by inhibiting CD36." (PMID 38276607, 2024).
hepatocellular carcinoma (continued). "Hence, we first investigated CD36+ CAFs in our cohort of resected HCC tissues from patients administered neoadjuvant anti-PD-1 therapy (toripalimab in combination with lenvatinib as neoadjuvant therapy for resectable hepatocellular carcinoma; clinical trial number: NCT03867370)." (PMID 36878933, 2023). "The increase in CD36 was confirmed in cultured human hepatoma cells, where either SIRT3 inhibition or knockdown in the presence of palmitate raised both CD36 and NQO1." (PMID 32912335, 2020). "The expression of fatty acid translocase CD36 elevates intracellular fatty acid levels and promotes EMT of hepatocellular carcinoma cells." (PMID 32327627, 2020). "Although CD36 expression has been correlated with EMT and metastasis in different tumor types (e.g. oral squamous cell carcinoma, hepatocellular cancer, and cervical cancer), the specific mechanisms remain controversial." (PMID 33232276, 2020). "In hepatocellular carcinoma (HCC), activation of CD36 expression to enhance the uptake of free fatty acids results in enhanced epithelial–mesenchymal transition and progression of HCC16." (PMID 30573731, 2018). "Small-molecule inhibitors targeting CD36, like Sulfosuccinimidyl oleate (SSO), significantly curtail fatty acid uptake, leading to the inhibition of ovarian cancer cell growth and the reduced migration of hepatocellular carcinoma (HCC) cells." (PMID 38610991, 2024). "Notably, hepatoma cells with GFP‐core protein expression presented with enhanced mRNA and protein levels of virus infection‐relevant receptors, including CD36, CD81, Claudin1, LDL R, and ACE2." (PMID 37316966, 2023). "Finally, a positive correlation between CD36 and FABP expression and EMT markers is observed in hepatocellular carcinoma (HCC) patients suffering of obesity." (PMID 35945203, 2022). "The overexpression of CD36 enhances the uptake of fatty acids and activates Wnt-dependent EMT in hepatocellular carcinoma (HCC)." (PMID 38994204, 2024). "Immunohistochemistry was performed on samples from patients with hepatocellular carcinoma (HCC) to establish the correlation between miR-3180, stearoyl-CoA desaturase-1 (SCD1), and CD36 expression, quantified via qRT-PCR and western blotting." (PMID 37041584, 2023). "For example, expression of fatty acid translocase CD36 elevates intracellular fatty acid levels and promotes EMT of hepatocellular carcinoma (HCC) cells." (PMID 31822964, 2020). "Although CD36 is not critically required for hepatic FFA uptake in humans, overexpression of CD36 in human hepatoma cell lines as well as forced expression of Cd36 in isolated mouse hepatocytes resulted in increased FFA uptake." (PMID 26085100, 2015).
hyperlipidemia (60 papers, 2010 to 2026). "A potential scenario to explain the increase in Trem2+ LAM and less inflammatory macrophages in CD36 deficient mice is that ATM CD36 expression is important for a pro-inflammatory response to hyperlipidemia but is dispensable for lipid uptake and catabolism." (PMID 39156133, 2024). "Alternatively, as we used CD36 full-body deficient animals, it is also possible that adipocyte CD36 mediates the pro-inflammatory response to hyperlipidemia and restricts Trem2+ LAM via adipocyte/macrophage crosstalk." (PMID 39156133, 2024). "A notable membrane protein pulled down by the E protein was CD36, a glycoprotein that has been implicated in mediating platelet activation and thrombosis under conditions of hyperlipidemia or inflammation." (PMID 37604832, 2023). "CD36 deficiency is closely related to the elevated prevalence of metabolic abnormalities, including hyperlipidemia, and increased fasting glucose levels." (PMID 35396566, 2022). "The contribution of platelet CD36 to hyperlipidemia-related thrombosis has previously been suggested, because the genetic deletion of CD36 in ApoE-deficient mice reduced the platelet hyperreactivity that promoted thrombosis." (PMID 34360659, 2021). "High levels of circulating oxLDL and cardiotonic steroid associated with hyperlipidemia induce oxidative stress and inflammation in the kidney by an interaction with CD36 and Na/K-ATPase, in both proximal tubule cells and their associated macrophages." (PMID 32796572, 2020). "The enhanced intestinal TG production may consequently cause postprandial hyperlipidemia in subjects with CD36-deficiency." (PMID 33995128, 2021). "In present study, using immunofluorescence and immunohistochemical staining we found an elevated expression of CD36 in the kidney of DN patients with hyperlipidemia, suggesting that CD36-mediated renal uptake of lipids might be associated with DN." (PMID 26000608, 2015). "This study showed that CD36-mediated oxidative stress was implicated in PA-induced FP effacement and may act as a novel therapeutic target for treating kidney disease accompanied by hyperlipidemia." (PMID 38584832, 2024). "This study showed that CD36-mediated oxidative stress was implicated in PA-induced FP effacement and may act as a novel therapeutic target for treating kidney damage accompanied by hyperlipidemia." (PMID 38584832, 2024). "Hyperlipidaemia worsens the outcome of ischaemic stroke by increasing CD36 expression in the post-ischaemic brain and in peripheral macrophages." (PMID 40565598, 2025). "These oxPCCD36 accumulate in vivo and mediate macrophage foam cell formation as well as promote platelet hyper-reactivity in hyperlipidemia via CD36." (PMID 39682740, 2024). "Nevertheless, as the engulfment of lipids increases, it gives a rise to secondary cytotoxic effects, and hyperlipidemia exasperates ischemic brain injury and mediates inflammation by promoting the upregulation of CD36 expression." (PMID 39054513, 2024). "The presence of hyperlipidemia will increase the transport of fatty acids to the kidneys and upregulate the Cluster of Differentiation 36 (CD36), leading to the enhanced uptake of FFA and the subsequent accumulation of fatty acids in the mitochondria." (PMID 38068746, 2023). "Oxidized phospholipids, ligands for CD36, which are known to accumulate in circulation in hyperlipidemia, induce a robust release of CD36 from several cell types." (PMID 40625574, 2023). "This study confirmed for the first time that the OxLDL receptor CD36 in renal tubular cells plays a role as an OxLDL receptor during hyperlipidaemia and oxidative stress." (PMID 36998992, 2023). "Yet, this unique expression pattern of CD36 within the adipose tissue provides a feed-forward inflammatory paracrine loop between adipocytes and ATMs in obese adipose tissue and hyperlipidemia conditions." (PMID 35438721, 2022).